CDK1 (cyclin dependent kinase 1)
Diseases named in the same sentence as CDK1 in open-access papers (continued):
Sharing a sentence is not in itself a finding about the gene and the disease.
lung adenocarcinoma (continued). "In fact, overexpression of CDK1 has been observed in early stage lung adenocarcinomas." (PMID 21887332, 2011). "We hypothesized that if regulated at the level of LINC00261 and CDK1, inhibiting IL-8 secretion and remodeling the tumor immune microenvironment might reverse immune resistance and improve the effectiveness of lung adenocarcinoma patients receiving immunotherapy." (PMID 36078096, 2022). "Therefore, screening the related pathway molecules that target CDK1 might be a potential effective way of research in lung adenocarcinoma prevention and treatment." (PMID 36078096, 2022). "This work aims to elucidate the oncogenic role of NiNPs via the CDK1/STAT3/FASN-FAM axis, propose API as a targeted intervention, and provide a scientific foundation for nanomaterial safety and lung adenocarcinoma prevention." (PMID 41226659, 2025). "Subsequent knockdown experiments targeting CDK1 and CCNB2 using both adenocarcinoma cell lines and LCOs demonstrated their inhibitory effects on the proliferation of lung adenocarcinoma." (PMID 37941550, 2023). "The strongest positive correlation was found for CDK1 (RS = 0.61) and LMNB1 (RS = 0.54) in lung adenocarcinoma." (PMID 35805937, 2022). "Mechanistically, Gliclazide inhibited the proliferation of lung adenocarcinoma cells possibly by targeting CCNB1, CCNB1, CDK1 and AURKA to induce cell cycle arrest and apoptosis." (PMID 34249701, 2021). "CENPA combined with CDK1 and CDC20 can serve as a cluster of prognostic biomarkers for lung adenocarcinoma." (PMID 32922438, 2020). "The results indicated that dried apricot polyphenols (DAPs) could cause cell cycle arrest in the G0/G1 and G2/M phases by decreasing the cyclin D1, CDK4, cyclin B1, CDK1, and CDK6 levels in A549 human lung adenocarcinoma cells." (PMID 39796398, 2025). "In addition, cyclin-dependent kinase 1 (CDK1), CCNB2, and CDC25A also exert tumor-promoting effects on the tumorigenesis and development of lung adenocarcinoma organoids." (PMID 35551634, 2022). "The results of molecular correlation analysis suggested that there was a significant negative correlation between LINC00261 and CDK1 in lung adenocarcinoma samples." (PMID 36078096, 2022). "In fact, combination of inhibition of CDK1 and PARP in BRCA-proficient cells resulted in reduced colony formation, tumor xenograft growth inhibition and tumor regression with prolonged survival in a mouse lung adenocarcinoma model, despite BRCA1 downregulation." (PMID 30002440, 2018). "utilized non-small cell LCOs to identify CDK1, CCNB2, and CDC25A as pivotal oncogenes in lung adenocarcinoma but not in lung squamous cell carcinoma." (PMID 37941550, 2023).
bladder cancer (40 papers, 2015 to 2025). "Additional research on bladder cancer cells revealed that cucurbitacin E-induced G2/M arrest might be associated with downregulation of pSTAT3, cyclin-dependent kinase 1 (CDK1), and cyclin B in human bladder cancer T24 Cells." (PMID 38397437, 2024). "In clinical samples of bladder cancer, activity of the CDK1/TFCP2L1 axis has been found to be associated with aggressive characteristics of tumors including advanced tumor grade, lymphovascular/muscularis-propria invasion, metastatic ability and poor clinical outcomes." (PMID 36266723, 2022). "Previous studies have demonstrated that inhibition of the PI3K/Akt pathway diminishes Cyclin B1 and CDK1 expression levels, thereby leading to the arrest of CC cells and bladder cancer cells in the G2/M phase." (PMID 37056992, 2023). "The present study and former experiments on bladder cancer cells revealed that CDK1 and 2 and their corresponding binding partners, Cyclin B and A, serve as crucial growth mediators." (PMID 37835543, 2023). "Another study has shown the role of CDK1 in phosphorylation of TFCP2L1 at Thr177 in embryonic stem cells of mice as well as human bladder cancer cells." (PMID 36266723, 2022). "Combination therapy with apigenin, a powerful antioxidant found in plants such as parsley and camomile, and a drug that inhibits the cell cycle protein CDK1 shows promise for developing therapies for bladder cancer (BC)." (PMID 35729325, 2022). "Expression of CDK1 has also been found to be increased in bladder cancer cells, parallel with over-expression of the long non-coding RNA (lncRNA) PVT1." (PMID 36266723, 2022). "The phosphorylation of transcription factor CP2-like 1 (TFCP2L1) by CDK1 at Thr177 promotes bladder carcinogenesis, and the tumorigenic potency of bladder cancer cells was reduced in a xenograft model when the level of TFCP2L1 phosphorylation was decreased." (PMID 35681641, 2022). "The physical and functional interaction between TFCP2L1 and CDK1 is conserved in human bladder cancer cells and modulates their proliferation and stemness features." (PMID 31709755, 2020). "Our phosphoproteomic data and bioinformatic analyses suggest two key activated kinases (GSK3A/B and CDK1) as potential druggable targets for the aggressive subtype of bladder carcinoma." (PMID 31108958, 2019). "We found that expression of cyclin B1 and Cdk1 are downregulated in bladder cancer cell lines treated with 9-ING-41." (PMID 31882719, 2019). "To investigate the mechanistic effect of GSK-3 inhibitor 9-ING-41 in the blockage of cell cycle in bladder cancer cells, we examined the expression of G2/M regulatory proteins Cdk1 and Cyclin B1 in 9-ING-41-treated cells." (PMID 31882719, 2019). "Former experiments on bladder cancer cell culture models showed that the cyclin B-cdk1 axis is also closely involved in tumor growth and proliferation, and that down-regulation of cyclin B/cdk1 causes a distinct delay in cell cycle progression." (PMID 29299126, 2017). "ATR-1 inhibited bladder cancer cell proliferation, arrested cell cycle in G2/M phase through up-regulation of p21 and down-regulation of cyclin B1, CDK1 and Cdc25c." (PMID 26931119, 2016). "Moreover, lncRNA PVT1 promoted proliferation, migration and invasion of bladder cancer cells by increasing the expression of CDK1 which down-regulated miR-31." (PMID 35193513, 2022). "Taken together, PVT1-mediated reduction of miR-31 could increase expression of CDK1 in bladder cancer cells to enhance their proliferative potential, migration, and invasion." (PMID 36266723, 2022). "Atractylenolide I, an active sesquiterpene component extracted from Rhizoma atractylodis, inhibits T24 bladder cancer cell proliferation by arresting the cell cycle in the G2/M phase via downregulation of cell cycle-related proteins such as CDK1, cell division cycle 25C (CDC25c), and cyclin B1." (PMID 33996570, 2021).
bladder cancer (continued). "Moreover, CDK1 was recently identified as the target of a competing endogenous RNA (ceRNA) mechanism (lncRNA PVT1/miR-31) in the facilitation of bladder cancer progression." (PMID 34499615, 2021). "Inhibition of the PI3K/AKT signal could decrease the levels of CyclinB1 and CDK1, thereby causing the G2/M cell cycle arrest in HCC cells and bladder cancer cells." (PMID 34642309, 2021). "Moreover, similar to our results, expression of cyclin B1 and Cdk1, mitotic entry regulatory proteins, were downregulated in bladder cancer cell lines treated with 9-ING-41." (PMID 34955846, 2021). "Thr177‐phosphorylation of TFCP2L1 by CDK1 stimulates pluripotency and cell cycling in embryonic stem cells and stemness features of bladder cancers, potentiating the tumorigenesis and aggressive behavior of bladder cancer." (PMID 31709755, 2020). "Here, we showed that CDK1 phosphorylation of TFCP2L1, a pluripotency‐associated transcription factor, orchestrated pluripotency and cell‐cycling in embryonic stem cells (ESCs) and was aberrantly activated in aggressive bladder cancers (BCs)." (PMID 31709755, 2020). "Nevertheless, the role of CDK1 in bladder carcinoma has yet to be elucidated." (PMID 31108958, 2019). "LncRNA PVT1 could enhance CDK1 expression via sponging miR-31 in bladder cancer." (PMID 32669972, 2020). "Mistletoe from Salicis specifically targeted CDK1 and 2, and Cyclin A, whereas mistletoe from Populi acted via CDK2 and Cyclin A and B. Low-grade bladder cancer appears to be more sensitive to mistletoe extracts than high-grade bladder cancer." (PMID 37835543, 2023). "CDK1/TFCP2L1 axis is also involved in the induction of stemness characteristics and tumorigenic ability of bladder cancer cells." (PMID 36266723, 2022). "The study provides the first direct experimental evidence that CDK1‐mediated phosphorylation of TFCP2L1 affects ESC function and promotes bladder cancer progression." (PMID 31709755, 2020). "Our results suggest that GSK-3 positively regulates the expression of cyclin B1 and Cdk1, and treatment with 9-ING-41 leads to cell cycle arrest at G2-phase in bladder cancer cells." (PMID 31882719, 2019). "AZD5438, a cyclin-dependent kinase-1/2/9 inhibitor, increased COX-2 expression by 1.6–3.5-fold in two out of six tested COX-2-expressing bladder cancer cell lines." (PMID 31497247, 2019). "We found that expression of Cdk1 and Cyclin B1 proteins was significantly decreased in 9-ING-41-treated bladder cancer cells." (PMID 31882719, 2019). "Specifically, CDK1, with an AUC value of 0.93, followed by PLK1 at 0.91 and AURKB at 0.90, showed the largest areas under the ROC curve, indicating their strong potential for distinguishing between bladder cancer and normal samples." (PMID 39456780, 2024). "Additionally, the correlation between CENPW expression and CDK1, CCNB1, and PCNA was further investigated in 10 bladder cancer tissue samples." (PMID 38213721, 2024). "However, CDK1 facilitates phosphorylation of TFCP2L1, activating embryonic stem cells in bladder cancer and driving tumorigenesis." (PMID 37196048, 2023). "In the current study, exposure of bladder cancer cells to isorhamnetin markedly reduced the expression of cyclin B1 and Wee1, without significant changes in the expression of Cdk1." (PMID 31590241, 2019). "Our study reveals GSK3A/B and CDK1 as promising druggable targets for the non-type molecular subtype, which could improve the treatment outcomes for aggressive bladder carcinoma." (PMID 31108958, 2019). "GSK3A/B and CDK1 could be potential druggable targets for the aggressive non-type bladder carcinoma." (PMID 31108958, 2019).
bladder cancer (continued). "In addition, analysis of TCGA expression data via gene expression profiling interactive analysis (GEPIA) demonstrated that CDK1, cyclinA2 and cyclinB1 are observed at increased expression levels in bladder cancer tissues, whereas CDK2, CDK4 and cyclinD1 are not differentially expressed." (PMID 40518827, 2025). "Importantly, previous studies have reported that CDK1 inhibitor RO-3306 exhibits tumor-selective cytotoxicity, demonstrating up to a fourfold greater cell-killing efficacy in bladder carcinoma and laryngeal squamous cell carcinoma models compared to normal epithelial cells." (PMID 40695806, 2025).
leukemia (32 papers, 2012 to 2025). A malignant (clonal) hematologic disorder, involving hematopoietic stem cells and characterized by the presence of primitive or atypical myeloid or lymphoid cells in the bone marrow and the blood. "Disruptions in this regulation are implicated in the onset and progression of leukaemia, highlighting the importance of the function of CDK1 in both normal and pathological states." (PMID 39762615, 2025). "Studies have shown that mutations in certain genes can induce overexpression of CDK1, promote tumor cell growth, migration, or invasion, and promote the occurrence of leukemia." (PMID 38464517, 2024). "DNMT3A mutation in mice promotes the development of leukemia by upregulating CDK1 through the mTOR pathway." (PMID 34093541, 2021). "Meanwhile, ampelopsin did not result in a significant reduction in the expression of CDK proteins, including CDK4, CDK2, and CDK1, in both leukemia cell lines." (PMID 33924032, 2021). "The regulation of the subcellular content of CDK1 and RARγ by all-trans retinoic acid is an important process for achieving an effective response in treatment of leukemia." (PMID 32596342, 2020). "We established a highly robust method for cell cycle analysis in U937 and MOLT4 human leukemia cell lines using CDK1 inhibitor RO-3306 for synchronizing cells in G2/M phase followed by sample collection and determination of cell cycle phase distribution with flow cytometry." (PMID 39774187, 2025). "Therefore, we aimed to identify reference genes characterized with stable expression throughout the cell cycle in MOLT4 and U937 human leukemia cell lines synchronized with RO-3306 CDK1 inhibitor using RT-qPCR." (PMID 39774187, 2025). "Inhibition of CDK1 due to the phosphorylation of the kinase on Tyr15 residue by flavonoids as well as induction of G2/M phase arrest and apoptosis by the flavonoid tamarixetin on human leukemia cells have previously been reported." (PMID 38099190, 2023). "In addition, a similar effect has been observed in FLT3-ITD leukemia cells in association with pronounced WEE-1 inhibition and diminished CDK1 Tyr15 phosphorylation." (PMID 25914884, 2015). "Importantly, whereas AZD-1775 treatment of leukemia cells triggered cyclin B/CDK1 (cdc2) Tyr15 dephosphorylation, it also induced Chk1 activation and Thr14 phosphorylation." (PMID 26113989, 2015). "In this context CDK1 inhibition may provide a therapeutic benefit in MLL-rearranged leukemia through its ability to block RUNX1." (PMID 25914884, 2015). "Similarly, administration CuE at 0.5–1 μM significantly inhibited the levels of pSTAT3 and CDK1, while when administration at 50 nM to human leukemia HL-60 cells it increased the levels of peIF2 and p21 while also decreasing the level of CDK1." (PMID 25072848, 2014). "Importantly, MJ-29-stimulated CDK1 activation appears to be acting the phosphorylation of Bcl-2 (Ser70), resulting in promotion of the intrinsic apoptotic signaling in human leukemia U937 cells." (PMID 22662126, 2012). "However, CDK1 gene expression was lower in leukemia and myeloma than in normal tissues." (PMID 36090896, 2022). "We have shown here that Cdk1 could phosphorylate p27 in human leukemia cells." (PMID 31822694, 2019). "The dynamic interaction between CDK1 and other key molecules, such as SPAG5, provides valuable targets for therapeutic intervention, aiming to disrupt the proliferative capacity of leukaemia cells and promote their elimination." (PMID 39762615, 2025). "In STK3-dependent leukemia, it was proposed that STK3 regulates cycle-dependent kinase 1 (CDK1) to drive cell proliferation." (PMID 37345153, 2023). "Coronopilin increases cyclin B1 and p-Cdk1 (Tyr15) levels; however, the upregulation of γH2AX (p-H2AX Ser139) is involved in G1 phase arrest in leukemia (Jurkat and U937) cells." (PMID 35651747, 2022). "A naturally derived small molecule CDK1 and AKT inhibitor terameprocol has shown safety and a partial response in some advanced leukemia patients." (PMID 34067359, 2021).
leukemia (continued). "Hence pharmacologic inhibitors of CDK1 may be useful for testing in FLT3-ITD driven leukemia." (PMID 25914884, 2015). "Also known as alvociclib, this wide spectrum CDK inhibitor targets CDK1, CDK2, CDK4, CDK6, CDK7 and CDK9 and displays antiproliferative efficacy in several solid tumours and sarcomas, as well as in leukaemia, lymphoma and multiple myeloma." (PMID 25625291, 2015). "Dinaciclib (SCH 727965, Merck) is a pyrazolo [1,5-α]pyrimidine that potently inhibits CDK1, CDK2, CDK5, and CDK9 with IC50 values ranging from 1 to 4 nM in a broad spectrum of human cancer cell lines including MCL, NHL, leukemia, colon, pancreatic, breast, prostate, SCLC, liver, and bladder." (PMID 25914884, 2015). "This discrepancy may, in part, reflect heterogeneity of p-Rb expression in different leukemia cells, but also suggests that, at least in some leukemias, the primary target of dinaciclib activity may not be CDK1/2." (PMID 23949430, 2013).